RNU7-62P (RNA, U7 small nuclear 62 pseudogene)
Synonyms: U7.62; LOC124904732
Gene: Small nuclear RNA gene on chromosome 1 (64,384,398 to 64,384,459, reverse strand). Ensembl gene ENSG00000238653.
Homologues: Orthologues: chimpanzee U7 (100% identical), macaque U7 (100% identical). Paralogues in human: RNU7-24P (87% identical), RNU7-34P (87% identical), U7 (87% identical), RNU7-21P (85% identical), RNU7-48P (85% identical), RNU7-55P (85% identical), RNU7-70P (85% identical), RNU7-7P (85% identical), RNU7-14P (84% identical), RNU7-20P (84% identical), RNU7-37P (84% identical), RNU7-40P (84% identical), and 143 more.